DEFB114 (defensin beta 114)
Description:
Has a salt-sensitive antimicrobial activity against Gram-negative bacteria, including E.coli, Gram-positive, including S.aureus, and fungi, including C.albicans. Binds to and neutralizes bacterial lipopolysaccharides (LPS), abolishing TNF production by macrophages challenged with LPS. Rescues the LPS-induced reduction of sperm motility in vitro and may protect from LPS-induced lethality.
Synonyms: DEFB-14; DEFB14
Tractability: Antibody: UniProt places it where antibodies can reach, with medium confidence; UniProt predicts a signal peptide or a membrane-spanning region; its Gene Ontology location is reachable by antibodies, with medium confidence.
Gene: Protein-coding gene on chromosome 6 (49,960,249 to 49,964,164, reverse strand). Ensembl gene ENSG00000177684.
Subcellular location: Secreted
Pathways (Reactome):
Immune System: Beta defensins; Defensins
Gene Ontology:
Molecular function: lipopolysaccharide binding; CCR6 chemokine receptor binding; chemoattractant activity
Biological process: antifungal innate immune response; defense response to Gram-negative bacterium; defense response to Gram-positive bacterium; innate immune response; negative regulation of lipopolysaccharide-mediated signaling pathway; negative regulation of MAP kinase activity; negative regulation of tumor necrosis factor production; positive regulation of inflammatory response; cell chemotaxis; defense response to bacterium; positive chemotaxis
Cellular component: extracellular region
Genetic constraint (gnomAD): Loss-of-function variants: 1 observed, 1.46 expected, observed/expected ratio (o/e) 0.69, 90% interval 0.21 to 1.84. That is too few expected variants to judge how well the gene tolerates losing a copy. Missense variants: 88 observed, 68.18 expected, observed/expected ratio (o/e) 1.29, 90% interval 1.09 to 1.54. Synonymous variants: 24 observed, 18.84 expected, observed/expected ratio (o/e) 1.27, 90% interval 0.92 to 1.76.
Homologues: Orthologues: chimpanzee DEFB114 (91% identical), macaque DEFB114 (90% identical), dog DEFB114 (65% identical), pig DEFB114 (62% identical), rabbit DEFB114 (55% identical).
Diseases named in the same sentence as DEFB114 in open-access papers:
DEFB114 is named in the same sentence as 5 diseases in open-access papers, as found by Europe PMC text mining. Sharing a sentence is not in itself a finding about the gene and the disease. The quoted sentences say what the papers report.
Cirrhosis (1 paper, 2012). A chronic disorder of the liver in which liver tissue becomes scarred and is partially replaced by regenerative nodules and fibrotic tissue resulting in loss of liver function. "ATG16L2, DEFB114, FAM14B, IFNA21, IL8RB and KIR2DL genes were up-regulated in cirrhosis, whereas, FCRL3, IFITM2 and OAS2 genes were up-regulated in initial fibrosis." (PMID 22397681, 2012).
DEFB114 also shares sentences with these, for which no sentence is quoted: psoriasis (2 papers); atopic dermatitis (1); E. coli infection (1); infection (1).